Y_RNA (Y RNA )
Gene: Miscellaneous RNA gene on chromosome 7 (90,251,923 to 90,252,020, forward strand). Ensembl gene ENSG00000207488.
Homologues: Orthologues: chimpanzee Y_RNA (98% identical). Paralogues in human: Y_RNA (85% identical), Y_RNA (84% identical), RNY3 (83% identical), RNY3P9 (83% identical), Y_RNA (83% identical), Y_RNA (82% identical), Y_RNA (81% identical), RNY3P1 (80% identical), RNY3P14 (80% identical), RNY3P2 (80% identical), Y_RNA (80% identical), Y_RNA (79% identical), and 91 more.